CIZ1 (CDKN1A interacting zinc finger protein 1)
Description:
May regulate the subcellular localization of CIP/WAF1.
Synonyms: LSFR1; NP94; ZNF356
Tractability: Antibody: its Gene Ontology location is reachable by antibodies, with high confidence. PROTAC: UniProt records ubiquitination sites on it; ubiquitination databases record sites on it; its protein half-life has been measured.
Gene: Protein-coding gene on chromosome 9 (128,161,251 to 128,204,482, reverse strand). Ensembl gene ENSG00000148337.
Subcellular location: Nucleus
Subcellular location (Human Protein Atlas): Nucleoplasm
Gene Ontology:
Molecular function: protein binding; zinc ion binding; nucleic acid binding
Cellular component: nucleoplasm; nucleus
Genetic constraint (gnomAD): Loss-of-function variants: 58 observed, 104.6 expected, observed/expected ratio (o/e) 0.55, 90% interval 0.45 to 0.69. The upper end of that interval is the gene's LOEUF score, 0.69, which puts it in group 2 of 6, group 1 being the genes least tolerant of losing a copy. Missense variants: 895 observed, 1,061.9 expected, observed/expected ratio (o/e) 0.84, 90% interval 0.8 to 0.89. Synonymous variants: 436 observed, 420.49 expected, observed/expected ratio (o/e) 1.04, 90% interval 0.96 to 1.12.
Homologues: Orthologues: chimpanzee CIZ1 (99% identical), macaque CIZ1 (93% identical), chimpanzee CIZ1 (92% identical), pig CIZ1 (78% identical), dog CIZ1 (76% identical), guinea pig CIZ1 (67% identical), rat Ciz1 (65% identical), mouse Ciz1 (64% identical), rabbit CIZ1 (53% identical), tropical clawed frog ciz1 (23% identical), zebrafish ciz1a (20% identical), zebrafish ciz1b (18% identical), and 2 more.
Diseases named in the same sentence as CIZ1 in open-access papers:
CIZ1 is named in the same sentence as 33 diseases in open-access papers, as found by Europe PMC text mining. Sharing a sentence is not in itself a finding about the gene and the disease. The quoted sentences say what the papers report.
Dystonia (11 papers, 2013 to 2025). An abnormally increased muscular tone that causes fixed abnormal postures. "Recently, CIZ1 is reported to be associated with Alzheimer’s disease, dystonia, and rheumatoid arthritis." (PMID 26861296, 2016). "CDKN1A directly interacts with the dystonia-associated protein CIZ1." (PMID 24936516, 2014). "Transcript variants of CIZ1 have been reported in a range of adult and pediatric cancers, as well as in neurological disorders including dystonias and Alzheimer’s disease, all of which could be affected via the same primary mechanism of weakened heterochromatin." (PMID 40067149, 2025). "Like these, other dystonia loci such as DYT23 (CIZ1) and DYT24 (ANO3) are yet to be independently confirmed." (PMID 29110692, 2017). "Additional isolated dystonia loci include DYT23 (CIZ1), DYT24 (ANO3), and DYT25 (GNAL), all of which have recently been extensively reviewed." (PMID 29110692, 2017). "In particular, five genes linked to dystonia appear to be involved upstream or downstream of DP-1 in the G1-S checkpoint pathway (ATM, CIZ1, TOR1A, THAP1 and TAF1)." (PMID 23849371, 2013). "In accordance with the scientific literature, we detected potentially relevant variations in known genes previously associated with CD and BSP, such as CIZ1, GNAL, and ANO3, and in other dystonia-related genes, such as KMT2B, VPS16, and KCNN2, for a total of nine patients." (PMID 37445923, 2023). "In this study, two patients had CIZ1 gene mutations, consistent with previous studies confirming that CIZ1 mutations were related to the pathogenesis of dystonia, but not in agreement with a recent study showing no CIZ1 mutations in blepharospasm patients." (PMID 32038460, 2019). "Whole exome sequencing also identified a CIZ1 polymorphism that has not been associated with dystonia." (PMID 23849371, 2013). "Therefore, CIZ1 may participate in the development of dystonia, but is only responsible for a small group of patients." (PMID 26861296, 2016). "Screening our data for proposed dystonia candidate genes identified presumably pathogenic variants in CHD6, KCNN2, KLC1, NR4A2, and ZMYND11, but not in others, for example, ATP5F1B, ACBD6, CIZ1, SHQ1, and SPTBN1." (PMID 40533913, 2025). "Sequencing of the other known PTD genes (THAP1, TUBB4a, CIZ1, ANO3, and GNAL) should be considered in patients with predominant cranial-cervical and laryngeal involvement, especially if family history is positive, with prioritization according to the age at onset and distribution of dystonia." (PMID 23596437, 2013).
Alzheimer disease (4 papers, 2015 to 2025). A progressive, neurodegenerative disease characterized by loss of function and death of nerve cells in several areas of the brain leading to loss of cognitive function such as memory and language. "In addition, splicing variants of CIZ1 mRNA is associated with a variety of cancers and Alzheimer’s disease, and mutations of the CIZ1 gene lead to cervical dystonia." (PMID 26861296, 2016). "Alternative splicing of CIZ1 is implicated in other chronic diseases including upregulation of a form in which part of exon 8 is excluded (CIZ1-S) in Alzheimer’s disease, and in cervical dystonia where mutations in an exonic splicing enhancer may affect splicing patterns." (PMID 30280956, 2018). "Thus, dysfunction of CIZ1 caused by missplicing in exon 8 could participate in the pathogenesis of Alzheimer’s disease by inhibition of proliferation and differentiation of neural progenitor cells." (PMID 26861296, 2016). "In the same MCF-7 cell populations we observed additional effects on CIZ1 alternative splicing, most notably increased CIZ1-S an isoform reported to be upregulated in Alzheimer’s disease, and changes in CIZ1-Δ4." (PMID 30280956, 2018). "In brain tissues of patients with Alzheimer’s disease, the variant CIZ1S level is specifically elevated in the hippocampus, and exhibits markedly higher expression level than full-length CIZ1." (PMID 26861296, 2016). "For example, EIS in the transcription factor CIZ1 changes protein localization, and the EI-spliced isoform is up-regulated in Alzheimer's disease brains." (PMID 25934563, 2015). "In addition to cancers, Alzheimer’s disease, and cervical dystonia,CIZ1 is found to be correlated with rheumatoid arthritis in a laser-mediated microdissection screening using synovial tissue samples with rheumatoid arthritis." (PMID 26861296, 2016). "In a subtractive cloning screen for novel candidate genes of Alzheimer’s disease, an alternative splicing variant of CIZ1 mRNA in exon 8 is moderately overexpressed in the hippocampus of patients with Alzheimer’s disease, and the level of full-length CIZ1 mRNA is not altered between the two groups." (PMID 26861296, 2016).
breast carcinoma (4 papers, 2016 to 2025). "Together these studies support the conclusion that excess expression of CIZ1 AD promotes the expression of genes linked with breast cancer." (PMID 40067149, 2025). "Together, these data show that C-terminal CIZ1 exons are over-represented in the majority of breast cancers, that epitopes encoded by C-terminal exons are uncoupled from N-terminal exons and pose the question of whether inappropriate AD protein is functionally relevant." (PMID 40067149, 2025). "We have exploited the easily visualized Xi-associated CIZ1 assemblies as an indicator of dysfunction in breast cancer cells and as a read out on the solubilizing action of CIZ1 DNFs in a murine model system." (PMID 40067149, 2025). "We conclude that CIZ1 protein and CIZ1–Xi assemblies are commonly disrupted in breast cancer cell lines." (PMID 40067149, 2025). "Focusing on breast cancer, we analyzed CIZ1 expression in 1,095 transcriptomes submitted to The Cancer Genome Atlas (TCGA)." (PMID 40067149, 2025). "To confirm that CIZ1-F is overrepresented in cancer tissue, and to extend our analysis of lung tumors, we analyzed CIZ1 mRNA in colon and breast cancer." (PMID 30280956, 2018). "CIZ1 has also been reported to be involved in the development of breast cancer, the most common type of cancer in women." (PMID 30280956, 2018). "In estrogen-sensitive breast cancer cell lines, Ciz1 is an estrogen receptor (ER)-dependent transcript that contributes to hypersensitization to estrogen-signaling pathways." (PMID 28036012, 2016). "Treatment with estrogen significantly increases the mRNA and protein level of CIZ1 in breast cancer cell lines." (PMID 26861296, 2016). "In estrogen-sensitive breast cancer cell lines, proliferation was dependent upon overexpression of Ciz1 for enhanced tumor growth in xenograft models and Ciz1-dependent tumor growth was blocked by siRNA-mediated depletion." (PMID 28036012, 2016). "We modeled the effect of AD on endogenous CIZ1–Xi assemblies and observed dominant-negative interference with their reformation after mitosis, leading to abnormal assemblies similar to those in breast cancer cells, and depletion of H2AK119ub1, H3K27me3, and Xist." (PMID 40067149, 2025). "However, in breast cancer–derived cell lines, the same anti-CIZ1 RD and anti-CIZ1 AD antibodies reveal considerable heterogeneity." (PMID 40067149, 2025). "Moreover, the N-terminal domain of CIZ1 protein can also interact with ER, conferring hypersensitivity to estrogen in animal models and enhancing the tumourigenicity of breast cancer cells." (PMID 30280956, 2018). "Ciz1 may promote tumor growth by contributing to deregulation of oncogenic transcription in breast cancer, colorectal carcinoma and gall bladder cancer." (PMID 28036012, 2016). "CIZ1 binds to estrogen receptors and increases the expression of estrogen downstream target genes and may contribute to the genesis of breast cancer." (PMID 26861296, 2016). "In addition, elevated expression of CIZ1 was observed in many malignancies including lung cancer, Ewing’s tumor, colon cancer, gallbladder cancer, prostate carcinoma, and breast cancer." (PMID 26861296, 2016). "Importantly, both SMAC buster sequence elevation in breast cancer cells and experimental DNF transgenes alter the transcriptome and, like deletion of CIZ1, effects are felt across the nucleus, with X-linked genes and other chromosomes similarly affected." (PMID 40067149, 2025). "For CIZ1, the common alteration observed here in breast cancers is not evident from overall expression level data, so it has not yet been captured by large-scale transcriptome studies." (PMID 40067149, 2025). "CIZ1 also interacts with estrogen-induced protein DLC1 to increase the activity of CDK2, which might contribute to proliferation of breast cancer cells." (PMID 26861296, 2016).
breast carcinoma (continued). "Furthermore, there are no recurrent polymorphisms in CIZ1 in adult cancers across 46,014 unique samples in COSMIC, so despite apparently profound effects on breast cancer gene expression, CIZ1 is not yet recognized as a “cancer” gene." (PMID 40067149, 2025).
lung carcinoma (4 papers, 2016 to 2018). "Exon 4 skipping in CIZ1 previously identified as a cancer variant, and reportedly used as an early serum biomarker in lung cancer was found." (PMID 30107825, 2018). "Variant CIZ1 has recently been published as a circulating biomarker for early-stage lung cancer suggesting the same might be possible for UVM patients." (PMID 30107825, 2018). "Our previous functional analysis of CIZ1 informed our understanding of the altered forms detected in lung cancer libraries, and led us to focus on CIZ1b, and then to identify CIZ1b protein in blood plasma." (PMID 27867087, 2017). "A unique protein epitope, created by alternative-splicing of the CIZ1 gene, is present in the plasma fraction of blood from patients with lung cancer, making it a strong candidate for high impact, high throughput early detection of lung cancer." (PMID 27867087, 2017). "In lung cancer, CIZ1 b-variant can classify 98% patients of lung cancer from normal controls." (PMID 26861296, 2016).
colon cancer (3 papers, 2016 to 2019). "In the present study, partial ES of CIZ1 exon 6 was associated with survival, and thus may be involved in the development of colon cancer." (PMID 31586988, 2019). "CIZ1 was found to be upregulated and associated with shorter survival in colon cancer patients." (PMID 31586988, 2019). "Significantly higher expressions of CIZ1 mRNA and protein are observed in colon cancer samples than adjacent tissues, and CIZ1 level is positively correlated with a poorer survival rate." (PMID 26861296, 2016).
prostate carcinoma (3 papers, 2016 to 2020). A carcinoma that arises from epithelial cells of the prostate gland. "Previous reports have shown overexpression of CIZ1 in colon, gallbladder, lung, and prostate cancer, as well as ependymomas, gliomas, and medulloblastomas, and it has also been reported that CIZ1 knockout mice develop leukaemias and lymphomas." (PMID 30280956, 2018). "CDC6, a CIZ1 partner in the formation of pre-replication complex, is down-regulated in prostate cancer, though CDC6 overexpression is considered to be oncogenic." (PMID 26861296, 2016). "Other studies also reveal the crucial roles of CIZ1 in the regulation of G1-S phase transition in prostate carcinoma cells and RKO colorectal cancer cells." (PMID 26861296, 2016). "It has been reported that knocking down CIZ1 in human prostate cancer cells reduced Akt expression." (PMID 33184261, 2020). "In addition, CIZ1 expression is found to be up-regulated in gallbladder cancer, prostate carcinoma, gastric cancer, and undifferentiated embryonic sarcoma of the liver." (PMID 26861296, 2016).
blepharospasm (2 papers, 2019 to 2023). "Only two patients had a family history of blepharospasm; mutations in SYNE1 and CIZ1 were detected in these patients, suggesting that mutations in SYNE1 and CIZ1 are the main genetic factors contributing to blepharospasm in these families." (PMID 38274886, 2023). "However, a follow-up study reported that all variants detected in GNAL, CIZ1, and TOR2A seemed to be benign in 132 blepharospasm patients." (PMID 32038460, 2019).
breast tumor (2 papers, 2018 to 2025). "Here, we show that CIZ1 C-terminal anchor domain (AD) is elevated in human breast tumor transcriptomes, even at stage I. Elevation correlates with deprotection of chromatin and upregulation of lncRNA-containing gene clusters in ∼10 Mb regions enriched in cancer-associated genes." (PMID 40067149, 2025).
cervical dystonia (2 papers, 2016 to 2018). "A conserved A–G mutation in exon 7 of the CIZ1 gene, which results in S264G substitution, is identified through exome screening of five members from a family with inherited cervical dystonia." (PMID 26861296, 2016). "In this context, cosegregating variants in CIZ1 and SETX were linked to cervical dystonia in a large American pedigree." (PMID 29770609, 2018).
gall bladder cancer (2 papers, 2016). "In gallbladder cancer, CIZ1 is found to interact with TCF4 and positively regulate Wnt signaling." (PMID 26861296, 2016). "Overexpression of CIZ1 increases the transcription of Wnt signaling target genes c-Myc, Snail, and Cyclin D1, and promotes the proliferation and migration of gallbladder cancer cells, while knockdown of CIZ1 remarkably inhibits gallbladder tumor formation in a xenograft mouse model." (PMID 26861296, 2016). "Similarly, Ciz1 transcript and protein levels were found to be significantly elevated in gall bladder cancer (GBC) cells." (PMID 28036012, 2016). "Ciz1 is associated with tumor growth in small cell (SCLC) and non-small cell lung carcinoma (NSCLC), colorectal, breast, prostate, hepatocellular carcinoma and gall bladder cancer." (PMID 28036012, 2016).
lymphoproliferative disorder (2 papers, 2019 to 2023). "The biological significance of CIZ1’s function is apparent in a CIZ1 null murine model which develops female specific lymphoproliferative disorder, and in the many human cancers of both sexes in which CIZ1 is dysregulated." (PMID 38155839, 2023).
colorectal carcinoma (1 paper, 2016). A malignant epithelial neoplasm that arises from the colon or rectum and invades through the muscularis mucosa into the submucosa. "Ciz1 is a potential prognostic marker of colorectal carcinoma (CRC)." (PMID 28036012, 2016).
Dysphonia (1 paper, 2023). Difficulty in speaking due to a physical disorder of the mouth, tongue, throat, or vocal cords. "A novel VUS, c.1820A>G (p.Glu607Gly) in the CIZ1 gene, was identified from a male CD patient whose symptoms of right-directed torticollis and dysphonia started at the age of 20." (PMID 37445923, 2023).
methamphetamine dependence (1 paper, 2025). A drug dependence that is a psychological dependency on the regular use of methamphetamine. "In contrast, ROC curve analysis indicated no diagnostic significance for methylation in the ATP6V1C1, CIZ1, GNG7 and LIAS genes concerning methamphetamine dependence." (PMID 41368944, 2025).
rheumatoid arthritis (1 paper, 2016). A chronic, systemic autoimmune disorder characterized by inflammation in the synovial membranes and articular surfaces. "CIZ1 expression is increased in cancers and rheumatoid arthritis." (PMID 26861296, 2016). "CIZ1 mRNA shows higher expression in rheumatoid arthritis samples than healthy controls." (PMID 26861296, 2016). "Unfortunately, no further information about the roles of CIZ1 in rheumatoid arthritis has ever been gained since then." (PMID 26861296, 2016).
thyroid tumor (1 paper, 2025). A benign or malignant neoplasm affecting the thyroid gland. "In addition, in some colon, lung, and thyroid tumors both RD and AD domains of CIZ1 were elevated compared with histologically normal tissue." (PMID 40067149, 2025).